MMP28 (matrix metallopeptidase 28)
Description:
Can degrade casein. Could play a role in tissues homeostasis and repair.
Synonyms: MMP-28; MMP-25; MM28; EPILYSIN
Tractability: Antibody: UniProt places it where antibodies can reach, with medium confidence; UniProt predicts a signal peptide or a membrane-spanning region; its Gene Ontology location is reachable by antibodies, with medium confidence.
Gene: Protein-coding gene on chromosome 17 (35,756,249 to 35,795,707, reverse strand). Ensembl gene ENSG00000271447.
Subcellular location: Secreted, extracellular space, extracellular matrix
Gene Ontology:
Molecular function: protein binding; metalloendopeptidase activity; metallopeptidase activity; zinc ion binding
Biological process: collagen catabolic process; extracellular matrix organization; proteolysis
Cellular component: extracellular matrix; cytoplasm
Genetic constraint (gnomAD): Loss-of-function variants: 55 observed, 53.78 expected, observed/expected ratio (o/e) 1.02, 90% interval 0.82 to 1.28. The upper end of that interval is the gene's LOEUF score, 1.28, which puts it in group 5 of 6, group 1 being the genes least tolerant of losing a copy. Missense variants: 686 observed, 697.7 expected, observed/expected ratio (o/e) 0.98, 90% interval 0.92 to 1.05. Synonymous variants: 318 observed, 282.61 expected, observed/expected ratio (o/e) 1.13, 90% interval 1.03 to 1.24.
Homologues: Orthologues: chimpanzee MMP28 (99% identical), macaque MMP28 (97% identical), dog MMP28 (89% identical), pig MMP28 (88% identical), rabbit MMP28 (87% identical), guinea pig MMP28 (86% identical), mouse Mmp28 (85% identical), rat Mmp28 (84% identical), tropical clawed frog mmp28 (52% identical), zebrafish mmp28 (50% identical), Caenorhabditis elegans zmp-3 (26% identical), Caenorhabditis elegans zmp-4 (20% identical), and 3 more. Paralogues in human: MMP15 (33% identical), MMP14 (32% identical), MMP16 (32% identical), MMP24 (31% identical), MMP10 (30% identical), MMP1 (30% identical), MMP19 (29% identical), MMP3 (29% identical), MMP17 (29% identical), MMP12 (29% identical), MMP13 (28% identical), MMP20 (28% identical), and 11 more.
Diseases named in the same sentence as MMP28 in open-access papers:
MMP28 is named in the same sentence as 68 diseases in open-access papers, as found by Europe PMC text mining. Sharing a sentence is not in itself a finding about the gene and the disease. The quoted sentences say what the papers report.
gastric cancer (13 papers, 2011 to 2023). A primary or metastatic malignant neoplasm involving the stomach. "Furthermore, MMP28 is associated with a poor prognosis and lower survival rates in gastric cancer and increased expression of MMP28 is associated with an increase in invasion and colony formation of gastric cancer cells in vitro and in vivo." (PMID 35008415, 2022). "Additionally, MMP28 is associated with invasion and colony formation in gastric cancer cells and increased MMP28 expression is a poor prognostic factor for gastric cancer patients." (PMID 35008415, 2022). "It has recently been found that KLF9 was able to inhibit the migration and invasion of gastric cancer cells and suppress tumor metastasis in vivo, which may be associated with the transcriptional regulation of MMP28." (PMID 34564711, 2021). "In previous studies, KLF9 suppressed human breast cancer invasiveness by downregulating matrix metalloproteinase 9 transcription and suppressed the invasion and metastasis of gastric cancer cells by inhibiting the transcription of MMP28." (PMID 37370046, 2023). "MMP28 promotes cell proliferation in oral squamous cell carcinoma, while in gastric cancer and hepatocellular carcinoma (HCC), there is a clear association with poor prognosis." (PMID 37590318, 2023). "Previously published data suggest that MMP28 plays a critical role in the regulation of metastasis in lung and gastric cancers." (PMID 35008415, 2022). "Some of the enriched epithelial genes or cytokine genes have been reported to get involved in cancer development and progression, for example, SERPINB5 in breast cancer, CCL3L1 in glioblastoma, CXC group in lung cancer, MMP28 in gastric cancer and so on." (PMID 32309224, 2020). "Further investigation revealed MMP28 is significantly correlated with invasive and metastatic ability and is a valuable marker of poor prognosis in gastric cancer." (PMID 21615884, 2011). "In the current study we have shown, to our knowledge for the first time, that MMP28 positively regulates invasion of gastric cancer cells in vitro and can induce a metastatic phenotype in vivo." (PMID 21615884, 2011). "This study provides the first evidence that MMP28 can promote invasion and metastasis in gastric cancer." (PMID 21615884, 2011). "The prognostic significance of MMP28 was assessed in 274 cases of gastric cancer with clinical follow-up records." (PMID 21615884, 2011). "In order to confirm this finding, MMP28 protein expression and invasive potential was examined in a range of human gastric cancer cell lines." (PMID 21615884, 2011). "This study indicates MMP28 is frequently overexpressed during progression of gastric carcinoma, and contributes to tumor cell invasion and metastasis." (PMID 21615884, 2011). "Kaplan-Meier survival analysis of 152 gastric carcinoma specimens revealed a significantly shorter overall survival times in tumors with higher MMP28 expression (p < 0.01)." (PMID 21615884, 2011). "This study also indicates MMP28 expression is significantly positively correlated with tumor invasion, lymph node metastasis and tumor-node-metastasis stage (p < 0.001), suggesting MMP28 plays a role in gastric carcinoma invasion and metastasis." (PMID 21615884, 2011). "Increased MMP28 expression in gastric carcinoma was correlated with depth of tumor invasion (p < 0.0001) and lymph node metastasis (p < 0.0001)." (PMID 21615884, 2011). "Ectopic expression of MMP28 indicated MMP28 promoted tumor cell invasion in vitro and increased gastric carcinoma metastasis in vivo." (PMID 21615884, 2011). "Our data demonstrates MMP28 is frequently overexpressed during gastric carcinoma progression and contributes to tumor cell invasion and metastasis." (PMID 21615884, 2011). "We evaluated the expression of MMP28 in 30 paired cases of gastric carcinoma tissue and normal epithelium." (PMID 21615884, 2011).
gastric cancer (continued). "We have established a gastric carcinoma invasion model using a highly invasive sub-line of tumor cells in which MMP28 was overexpressed." (PMID 21615884, 2011). "Immunohistochemical analysis revealed MMP28 is overexpressed in gastric carcinoma relative to normal epithelial cells, and MMP28 is significantly associated with depth of tumor invasion, lymph node metastasis and a poorer overall survival." (PMID 21615884, 2011). "Immunohistochemistry revealed MMP28 expression was markedly increased in gastric carcinoma relative to normal epithelia, and was significantly associated with depth of tumor invasion, lymph node metastasis and poorer overall survival." (PMID 21615884, 2011). "MMP28 is involved in the occurrence and metastasis of gastric cancer and CRC." (PMID 36059637, 2022). "MMP28 is associated with metastasis in lung and gastric cancer, but has not yet been studied in CRC." (PMID 35008415, 2022). "MMP28 immunohistochemistry was performed in normal and gastric cancer specimens." (PMID 21615884, 2011). "Cox multivariate analysis of MMP28 expression and clinico-pathological features in gastric cancer." (PMID 21615884, 2011). "Taken together, these data indicate MMP28 plays an important role in gastric cancer progression." (PMID 21615884, 2011). "MMP28 may be a novel therapeutic target for prevention and treatment of metastases in gastric cancer." (PMID 21615884, 2011). "Furthermore, multivariate analysis revealed that MMP28 was an independent prognostic factor in gastric cancer." (PMID 21615884, 2011). "KLF9 is obviously downregulated in patients with gastric cancer (GC) and KLF9 significantly inhibits the invasion and metastasis of GC cells through inhibiting the MMP28 transcription." (PMID 34612136, 2021). "MMP28 protein was expressed in gastric cancer cells and lymph node metastasis and not located in the surrounding normal tissues." (PMID 21615884, 2011).
colorectal cancer (6 papers, 2015 to 2024). A primary or metastatic malignant neoplasm that affects the colon or rectum. "Controversial studies reported the role of SFN in potentiating colon tumorigenesis through the activation of various factors, such as matrix metalloproteinase 28 (MMP28), which contributed to the progression of colorectal cancer." (PMID 38528462, 2024). "Our data demonstrates that MMP28 cleaves and decreases expression of E-cadherin, a marker for epithelial-to-mesenchymal transition in colorectal cancers." (PMID 35008415, 2022). "β-Carotene reduces invasiveness with a decreased expression of MMP-7 and MMP-28 in colorectal carcinoma cells." (PMID 33809289, 2021). "Consistent with our finding here, the downregulation of MMP28 in colorectal cancers has been validated in detailed analysis of MMP gene expression patterns." (PMID 26356760, 2015). "Here, in studying the role of CD36 in colorectal cancer, we found that CD36 promotes colorectal cancer invasion in vitro and metastasis in vivo and that overexpression of CD36 upregulates expression of the matrix metalloproteinase MMP28." (PMID 35008415, 2022). "MiR-144 was markedly down-regulated in colorectal cancer cells and suppressed the expression of GSPT1 to regulate the cell proliferation-related gene expressions of c-myc, survivin and Bcl2L15 and metastasis-related factor MMP28." (PMID 30126852, 2018).
lung carcinoma (6 papers, 2011 to 2023). "Lastly, MMP28-induced EMT in lung carcinoma is associated with a significant loss of E-cadherin expression." (PMID 35008415, 2022). "Specifically, MMP28 has been shown to promote EMT in lung carcinoma and increased expression of MMP28 is associated with a loss of E-cadherin." (PMID 35008415, 2022). "MMP28, one of the newest members of this family of proteins to be identified, is associated with EMT in lung carcinoma." (PMID 35008415, 2022). "MMP-28 overexpression in vitro lead to increased MMP-2 and MMP-14 mRNA levels, constitutive MMP-2 activation, and revealed e-cadherin as a high-affinity substrate for proteasomal degradation in lung carcinoma cells." (PMID 34255809, 2021). "Moreover, MMP28 is expressed in many cancers 48 and has been shown to induce EMT in lung cancer through the TGF-β signaling pathway, thereby promoting invasion." (PMID 33033514, 2020). "Given that MMP28 was previously shown to favour EMT via an extracellular effect on the TGFβ pathway in lung carcinoma cell lines, the authors of the HCC study did not investigate whether MMP28 could act directly from within the cells." (PMID 37590318, 2023).
myocardial infarction (6 papers, 2015 to 2021). Gross necrosis of the myocardium, as a result of interruption of the blood supply to the area, as in coronary thrombosis. "It has been reported that MMP-28 participates in the process of myocardial remodeling after myocardial infarction, and it has some correlation with the severity of coronary artery disease." (PMID 32596395, 2020). "However, the role of MMP-28 in acute myocardial infarction and its correlation with coronary artery disease remain to be elucidated." (PMID 32596395, 2020). "Circulating MMP-28, a new member in the family of MMPs, could be considered a predictor for short-term prognosis in patients with myocardial infarction." (PMID 33614740, 2020). "In contrast to MMP-2 and MMP-9 where myocardial infarction (MI) induced increase of their levels/activities, MMP-28 levels decreased post-MI." (PMID 33923282, 2021). "In this study, it was also observed that MMP-28 is closely related to the indices of cardiac function, such as NT-proBNP and LVEF in the population with myocardial infarction." (PMID 32596395, 2020).
pancreatic cancer (6 papers, 2015 to 2025). "Our preliminary findings revealed that high MMP28 expression in pancreatic cancer tissues was associated with poor prognosis (unpublished)." (PMID 39972459, 2025). "Collectively, these findings indicate that MMP28 plays a critical role in pancreatic cancer progression and is intimately linked to tumor microenvironment remodeling." (PMID 39972459, 2025). "However, the precise molecular mechanisms underlying the impact of MMP28 on pancreatic cancer and its microenvironment require further elucidation." (PMID 39972459, 2025). "EdU staining and CCK-8 assays demonstrated a decrease in cell proliferation following MMP28 knockdown and a significant increase in proliferation upon MMP28 overexpression in both pancreatic cancer cell lines." (PMID 39972459, 2025). "While the role of MMP28 in pancreatic cancer remains incompletely understood, previous research has indicated its potential importance." (PMID 39972459, 2025). "Collectively, the presented data provide compelling evidence that MMP28 enhances pancreatic cancer growth and M2 TAM infiltration in vivo." (PMID 39972459, 2025). "To further explore the signaling pathways mediating the role of MMP28 in cytokine secretion by pancreatic cancer cells, we investigated MAPK pathways known to be involved in cell migration and cytokine regulation." (PMID 39972459, 2025). "Immunohistochemical staining and qRT-PCR were used to validate MMP28 as a potential marker for the prognosis of patients with pancreatic cancer." (PMID 39972459, 2025). "The GEPIA database confirmed a strong association between MMP28 and ANXA2 expression in pancreatic cancer." (PMID 39972459, 2025). "The impact of MMP28 on pancreatic cancer growth and TAMs was partially reversed by inhibiting either the JNK signaling pathway or the effects of IL-8 and VEGFA." (PMID 39972459, 2025). "Previous single-cell RNA sequencing studies revealed that MMP28 is expressed predominantly within pancreatic ductal epithelial cells, highlighting the specific expression of MMP28 in pancreatic cancer." (PMID 39972459, 2025). "Briefly, MMP28, which is overexpressed in pancreatic cancer, mediates the recruitment of TAMs through phosphorylation of the MAPK/JNK signaling pathway, stimulating the secretion of IL-8 and VEGFA by cancer cells." (PMID 39972459, 2025). "In conclusion, these findings collectively suggest that MMP28 promotes pancreatic cancer cell proliferation, migration, and invasion and inhibits apoptosis, thereby contributing to promoting malignant progression." (PMID 39972459, 2025). "Collectively, our findings elucidate a novel mechanism by which pancreatic cancer cells manipulate the tumor microenvironment through MMP28-dependent cytokine secretion, promoting TAM infiltration and M2 polarization." (PMID 39972459, 2025). "In conclusion, the MMP28 expression levels in most pancreatic cancer cell lines were higher than in the normal pancreatic cell line." (PMID 37821678, 2023). "Compared with other tumor cell lines, the mRNA expression level of MMP28 was high in pancreatic cancer cell lines." (PMID 37821678, 2023). "Lastly, expression of MMP28 in pancreatic cancer cell lines and normal pancreatic cells was determined using real-time quantitative PCR (RT-qPCR)." (PMID 37821678, 2023). "Next, we measured expression of MMP28 in pancreatic cancer cell lines and normal pancreatic cells using RT-qPCR." (PMID 37821678, 2023). "The relationship between MMP28 expression and pancreatic cancer progression was investigated using the UALCAN database." (PMID 37821678, 2023). "Taken together, the evidence strongly suggests that MMP28 has potential as a prognostic biomarker for pancreatic cancer patients." (PMID 37821678, 2023). "Martínez-Bosch and colleagues proved that PARP-1 upregulates MDM2, VEGFR1, and MMP28, accelerating tumor proliferation and angiogenesis in pancreatic cancer." (PMID 26314963, 2015).
pancreatic cancer (continued). "Consequently, our findings establish that MMP28, which is overexpressed in pancreatic cancer, is a key driver of tumor progression through its interaction with TAMs within the microenvironment, revealing a novel function for this protein." (PMID 39972459, 2025). "This study investigated the role of MMP28 in pancreatic cancer progression." (PMID 39972459, 2025). "Furthermore, ANXA2 expression was also increased in MMP28-overexpressing pancreatic cancer cells, and ANXA2 knockdown partially inhibited the ability of MMP28 to promote JNK phosphorylation." (PMID 39972459, 2025). "And MMP28 was highly expressed in various pancreatic cancer cell lines." (PMID 37821678, 2023). "The relevant results of this study revealed a strong correlation between MMP28 expression and TAM infiltration, with a predominance of M2-polarized TAMs in pancreatic cancer tissues." (PMID 39972459, 2025). "Increased MMP28 expression, elevated CD163 + TAMs, and reduced CD86 + TAMs were significantly correlated with the pancreatic cancer site (P < 0.05)." (PMID 39972459, 2025). "Collectively, these findings unequivocally support the pivotal role of MMP28 in inducing TAM migration and promoting M2 TAM polarization in pancreatic cancer cells." (PMID 39972459, 2025). "The present study demonstrated that tumor-derived MMP28 promotes TAM recruitment and induces M2 TAM polarization, thereby enhancing pancreatic cancer growth and proliferation in vitro and in vivo." (PMID 39972459, 2025). "Our findings suggest that MMP28 enhances TAM recruitment and M2 polarization by stimulating cytokine secretion through the MAPK/JNK pathway, providing novel insights into potential therapeutic targets for pancreatic cancer." (PMID 39972459, 2025). "Bioinformatics analysis revealed substantial upregulation of MMP28 in pancreatic cancer tissues compared with that in their noncancerous counterparts, which was concomitantly associated with an unfavorable prognosis." (PMID 39972459, 2025). "Furthermore, ANXA2 amplifies MMP28-mediated M2 TAM infiltration, collectively contributing to the malignant progression of pancreatic cancer." (PMID 39972459, 2025). "Subsequent qRT-PCR analysis of 68 pancreatic cancer and adjacent noncancerous tissues samples confirmed elevated MMP28 and CD163 mRNA levels, whereas CD86 mRNA expression was lower in cancer tissues than in noncancerous controls." (PMID 39972459, 2025). "To understanding the function of MMP28, using the UALCAN database, we explored a list of co-expressed genes in PDAC that may play a synergistic role in the progression of pancreatic cancer." (PMID 37821678, 2023). "Immunohistochemical staining of 36 randomly selected pancreatic cancer clinical samples revealed a positive correlation between MMP28 and CD163 (P < 0.05), but a negative correlation between MMP28 and CD86 (P < 0.001), suggesting a close association between MMP28 and CD163 + TAM infiltration." (PMID 39972459, 2025). "Moreover, inhibiting ANXA2 expression partially reversed the effects of MMP28 on TAMs, suggesting that the MMP28-ANXA2 interaction influences TAM infiltration and polarization, thereby representing a potential therapeutic target for TAM-based pancreatic cancer treatments." (PMID 39972459, 2025).